TMEFF2 (transmembrane protein with EGF like and two follistatin like domains 2)
Diseases named in the same sentence as TMEFF2 in open-access papers (continued):
Sharing a sentence is not in itself a finding about the gene and the disease.
asthma (1 paper, 2024). "TMEFF2 was genetically associated with submucosal eosinophils in bronchial brushing samples of patients with severe asthma." (PMID 38750426, 2024). "The GWAS comparing individuals with severe COVID-19 with asthma to those without asthma revealed four genetic variants in transmembrane protein with EGF like and two follistatin like domains 2 (TMEFF2) and huntingtin interacting protein-1 (HIP1) genes." (PMID 38750426, 2024).
cardiac hypertrophy (1 paper, 2022). "TMEFF2 has been linked to hypertension and cardiac hypertrophy, according to previous research." (PMID 35629146, 2022).
esophageal cancer (1 paper, 2011). A primary or metastatic malignant neoplasm involving the esophagus. "The significance of the previously reported hypermethylation of TMEFF2 gene in humancancers including colorectal, gastric and esophageal cancers is confounded by the low levelsof TMEFF2 expression in normal tissues of these origins." (PMID 21559523, 2011). "Hypermethylation of the TMEFF2 gene in human cancers has been reported in severaltissues including colorectal, gastric and esophageal cancers." (PMID 21559523, 2011).
gastric tumours (1 paper, 2020). "DNA damage-related genes were found to be enriched in TMEFF2 overexpressing AGS cells and gastric tumours with high TMEFF2 expression levels." (PMID 33371267, 2020).
melanoma (1 paper, 2021). A malignant, usually aggressive tumor composed of atypical, neoplastic melanocytes. "All but ESR1, PAX8, PGR, TMEFF2, were associated with prognosis of breast, cervical, colorectal, head and neck, liver, lung, melanoma, ovarian, pancreatic, renal, or urothelial cancers." (PMID 34680205, 2021).
neuroblastoma (1 paper, 2014). Neuroblastoma (NB) is the most common solid, extracranial childhood tumor. "TMEFF2 is a PDGF-AA binding protein associated with gene silencing, while PDGF-AA is known to be functional in neuroblastoma cell growth." (PMID 25295525, 2014).
thyroid tumor (1 paper, 2023). A benign or malignant neoplasm affecting the thyroid gland. "PTGS2, HOXA1, TMEFF2, p16, and PTEN genes were hypermethylated in FNAC of thyroid tumor when compared between the tumor and healthy tissue." (PMID 36975440, 2023).
tumor (39 papers, 2009 to 2025). "We used RNA interference experiments in PCa cell lines to identify a gene expression based gene signature associated with Tmeff2, an androgen regulated, tumor suppressor gene whose expression shows remarkable heterogeneity in PCa." (PMID 31060542, 2019). "We first analyzed tumor associated changes in TMEFF2 expression by immunohistochemistry in PCa tissues." (PMID 31060542, 2019). "TMEFF2 shedding is increased with cell crowding, a condition associated with the tumour microenvironment, which was mediated by oxidative stress signalling, requiring jun‐kinase (JNK) activation." (PMID 28762604, 2018). "Interestingly, TMEFF2 (transmembrane protein with egf-like and two follistatin-like domains 2), which encodes the single-pass transmembrane protein Tomoregulin-2, is described as a tumor suppressor protein." (PMID 35565454, 2022). "It is worth noting that SHP-1 protein encoded by PTPN6 mediates the tumor-suppressive function of TMEFF2 in STAD, which indicates expression of PTPN6 might influence the carcinogenesis of STAD patients." (PMID 32536826, 2020). "The CAR itself, containing a human germline antibody 3-23/B3-derived scFv is inert on its own but paired with AM targeting PSMA or TMEFF2 (tomoregulin-2) it enabled dose-dependent tumour lysis and cytokine secretion." (PMID 41465327, 2025). "TMEFF2 is a transmembrane protein in the tomoregulin family that is hypermethylated and underexpressed in various tumour types." (PMID 33663520, 2021). "The results showed that patients whose primary tumours showed low TMEFF2 methylation achieved longer survival and a better prognosis than patients whose primary tumours exhibited high TMEFF2 methylation (HR = 0.35, P < 0.001)." (PMID 33663520, 2021). "Further molecular, cellular, and animal model studies should be performed to achieve a comprehensive understanding of the mechanism of TMEFF2 in carcinogenesis and tumour progression in adult diffuse gliomas." (PMID 33663520, 2021). "TMEFF2 is one of the top 100 mRNA transcripts with the highest levels of inter-tumor variability in patient samples from several publically available datasets." (PMID 31060542, 2019). "A recent report lists TMEFF2 as one of the top 100 mRNA transcripts with the highest levels of inter-tumor variability in primary PCa tissues." (PMID 31060542, 2019). "Full length TMEFF2 also attenuates the migratory properties of PCa cells, indicating a tumour suppressor function." (PMID 28762604, 2018). "Hypermethylation was associated with advanced tumor stage for ABCC6 (P = 0.050), BRCA1 (P = 0.032), CDH1 (P = 0.004), GDF15 (P = 0.005), HSPA2 (P = 0.000), RASSF1A (P = 0.003), TSHB1 (P = 0.018), and TMEFF2 (P = 0.002)." (PMID 25613404, 2015). "We have previously demonstrated that the tumor suppressor ability of TMEFF2 partly correlates with its ability to interact with SARDH and modulate the levels of sarcosine." (PMID 23405127, 2013). "TMEFF2 is mainly expressed in the adult brain and prostate where it plays a role as a tumor suppressor." (PMID 23405127, 2013). "In fact, we have also established that full-length TMEFF2 functions as a tumor suppressor and that this role correlates, at least in part, with its ability to interact with SARDH and modulate the cellular levels of sarcosine." (PMID 23405127, 2013). "We show that expression of TMEFF2 negatively correlates withits methylation levels in GBM and several other tumor types, further supporting apossible tumor suppressor role of TMEFF2 in these tissues." (PMID 21559523, 2011). "Here we reporthypermethylation of TMEFF2 in several additional tumor types, including GBM, where aclear down-regulation is observed compared to high levels of TMEFF2 expression innormal brain tissues." (PMID 21559523, 2011).
tumor (continued). "Our findings not only suggest a connection between the role of TMEFF2 in PDGFsignaling and the potential tumor suppressor function of TMEFF2, but also providepossible explanations for the seemingly conflicting roles of TMEFF2 in humancancers." (PMID 21559523, 2011). "The 5′-region of TMEFF2 gene is frequently hypermethylated in some cancers, suggestinga possible tumor suppressor role for TMEFF2 in these cancers." (PMID 21559523, 2011). "TMEFF2 expression in tumour specimens was lower than that in peritumoural specimens (P < 0.001)." (PMID 33663520, 2021). "Interestingly, TMEFF2 can act as a promotor as well as suppressor during tumour progression, depending on alternative splicing and ectodomain shedding." (PMID 33663520, 2021). "Our studies in PCa demonstrate a role of TMEFF2 as a tumor suppressor." (PMID 31060542, 2019). "However, when patients were stratified by tumor stage, TMEFF2 expression was significantly decreased in more advanced pathological stages." (PMID 31060542, 2019). "TMEFF2 is significantly downregulated in corticotropinomas relative to control tissues, which suggests that TMEFF2 might be a tumor suppressor." (PMID 31231308, 2019). "Our data have not demonstrated whether TMEFF2 methylation is associated with malignant tumour transformation during tumour recurrence." (PMID 33663520, 2021). "More studies could be performed to clarify the role of TMEFF2 methylation in tumour recurrence." (PMID 33663520, 2021). "For example, cells in immune_2 and immune_1 are surrounded by tumor cells and stroma cells, respectively, and have distinct expression patterns of marker genes such as CNN1, DES, and TMEFF2." (PMID 39960663, 2025). "In line with our previous observations, the tumor markers AMACR, CAMKK2, TMEFF2, REPS2 and ABCC4 were significantly expressed in AMACR high cells as compared to AMACR low cells." (PMID 25514598, 2015). "Some tumor markers such as AMACR, TMEFF2 and ABCC4 were also expressed in mesenchymal cells or lymphocytes at levels comparable to AMACR low cells." (PMID 25514598, 2015). "Next, 200 cells from the high and low gate were sorted for qPCR analysis for a subset of tumor markers such as AMACR, CAMKK2, TMEFF2, REPS2 and ABCC4." (PMID 25514598, 2015). "DNA methylation at the promoter region of the MGMT, CDKN2A, SFRP1, TMEFF2, HS3ST2 (3OST2), RASSF1A and GATA4 genes was evaluated by quantitative methylation specific PCR in both tumor and corresponding normal appearing colorectal mucosa samples." (PMID 20098741, 2010). "TMEFF2 protein expression was higher in patients with localized disease as compared to non-tumor samples (not shown)." (PMID 31060542, 2019). "Of these, CAV1, SFRP2, TMEFF2, SST and SLIT2 have been identified as tumor-suppressor genes." (PMID 25997610, 2015). "It is possible that TMEFF2serves as a tumor suppressor in normal brain by inhibiting signaling via PDGF-AA.Hypermethylation and downregulation of TMEFF2 may facilitate tumorigenesis in thetumors that express high levels of PDGF-A by releasing this inhibition." (PMID 21559523, 2011). "Common up-regulation of genes such as COL1A1, COL1A2, PGF, LRRFIP1, TMEFF2 or TGFB1 suggested an important role of this pool of cells in blood vessel formation, angiogenesis, permeability and proliferation pathways, essentials functions in tumour progression." (PMID 20735813, 2010). "They found TMEFF2 methylation in 29/316 samples and no TMEFF2 methylation in control samples, and when compared to corresponding solid tumor samples, three serum cfDNA samples matched tumor DNA samples." (PMID 27589834, 2016).
cancer (21 papers, 2008 to 2025). A tumor composed of atypical neoplastic, often pleomorphic cells that invade other tissues. "Numerous primary publications suggest the methylation of TMEFF2 as a prognostic and even diagnostic marker in different cancers." (PMID 33371267, 2020). "Specific genes, including SEPT9, VIM1 and TMEFF2 become methylated in a high fraction of cancers and diagnostic assays for detection of cancer-derived methylated DNA sequences in blood and/or fecal samples are being developed." (PMID 24485021, 2014). "Gene differential expression analysis revealed that cancer cell subgroup 1 was characterized by high expression of genes such as TMEFF2, subgroup 2 by high expression of genes such as RGS1, and subgroup 3 by high expression of genes such as CLDN11." (PMID 40843359, 2025). "The HCT-116 cell line is resistant to interferon therapy (like several other cancers), and an interesting observation from this study was that TMEFF2 overexpression marginally sensitized HCT-116 cells to INF-α but not INF-γ." (PMID 33371267, 2020). "Because of its implication in numerous cancers and involvement in diverse functions, TMEFF2 has attracted considerable interest since its identification in 2000; however, TMEFF2-related data appears inconsistent and sometimes conflicting across studies." (PMID 33371267, 2020). "TMEFF2 is methylated in numerous cancers, and an inverse correlation with the stage, response to therapy and survival outcome has been observed." (PMID 33371267, 2020). "This study not only provides new insights into the clinical relevance of Tmeff2 in cancer, but also specifies a group of cell cycle related genes as prognostic and potential therapeutic targets." (PMID 31060542, 2019). "Low levels of TMEFF2 mRNA significantly (p < 0.0001) correlated with reduced disease-free survival (DFS) in patients from the Memorial Sloan Kettering Cancer Center (MSKCC) dataset." (PMID 31060542, 2019). "We thus identified two loci, HOXA1 and TMEFF2, that appear to have an “intermediate” role in cancer development in the lung as well as the breast." (PMID 21731750, 2011). "Togetherthese data suggest an important role of TMEFF2 in the development and progression ofhuman cancers." (PMID 21559523, 2011). "Moreover, the TMEFF2 promoter and 5′-upstream regions harbour a CpG island which is progressively methylated upon progression in a wide variety of cancers." (PMID 33371267, 2020). "The biological function of TMEFF2 remains unclearwith conflicting reports suggesting both a positive and a negativeassociation between TMEFF2 expression and human cancers." (PMID 21559523, 2011). "Moreover, the 5′-region ofTMEFF2 gene is frequently hypermethylated in some cancers, suggesting a possible tumorsuppressor role of TMEFF2 in these cancers." (PMID 21559523, 2011). "Furthermore, the extent of methylation was significantly greater in EAC compared to BE for six genes (CDKN2A, ID4, RBP1, RUNX3, SFRP1, and TMEFF2), suggesting that methylation of these genes occurs early in the progression of BE, with increased methylation as the disease advances toward cancer." (PMID 40149421, 2025). "Several studies among these are indicative of a direct correlation between TMEFF2 mRNA downregulation and its promoter methylation, and some also reported promoter methylation to be related to the stages, response to therapy and survival outcomes of the corresponding cancers." (PMID 33371267, 2020). "Similarly to Satb1 and Hoxa1, Tmeff2 and Enpp2 are up regulated in carcinomas." (PMID 21054883, 2010). "Our data provide the first evidence that TMEFF2 canfunction to regulate PDGF signaling, and give new mechanistic insights into theseemingly conflicting roles of TMEFF2 in human cancers." (PMID 21559523, 2011).
cancer (continued). "Besides the five cancer driver genes, we found that TMEFF2 (also known as HPP1), hypermethylated in 95.52% of the 268 CRC samples, was hypermethylated and downregulated in all the 16 cancer tissues compared with their paired adjacent normal tissues." (PMID 28537885, 2017).
TMEFF2 also shares sentences with these, for which no sentence is quoted: adenocarcinoma (3 papers); colon cancer (2); dysplasia (2); esophageal adenocarcinoma (2); lung adenocarcinoma (2); adenoma (1); brain cancer (1); brain tumour (1); cervical cancer (1); COVID-19 (1); epilepsy (1); gastrointestinal stromal tumor (1); Hypertension (1); metastatic colorectal cancer (1); ovarian carcinoma (1); popliteal pterygium syndrome (1); prostate (1); rectal adenocarcinoma (1); squamous cell carcinoma (1); squamous intraepithelial lesions (1).